GPNMB (glycoprotein nmb)
Diseases named in the same sentence as GPNMB in open-access papers (continued):
Sharing a sentence is not in itself a finding about the gene and the disease.
bladder cancer (3 papers, 2018 to 2024). "While we found no significant prognostic evidence when analysing GPNMB RNA levels in bulk sequencing, high GPNMB levels measured by immunohistochemistry in bladder cancer was previously correlated with a worse prognosis." (PMID 38890455, 2024). "Immunofluorescence staining confirmed expression of GPNMB within the tumour regions in bladder cancer, mirroring the tumour localisation seen in the DSP dataset." (PMID 38890455, 2024). "Similarly, the researchers attenuated the proliferation and migration of bladder cancer cells through GPNMB gene knockout while reducing the expression of MMP-2, MMP-9, and β-catenin and demonstrated that high GPNMB expression is a risk factor for bladder cancer." (PMID 36090016, 2022). "Another limitation of our study was a lack of tissue available for follow-up experiments to confirm the interaction between GPNMB and VEGFA in bladder cancer." (PMID 38890455, 2024).
colon cancer (3 papers, 2009 to 2018). "Expression levels of GPNMB at different cancer stages were analyzed and substantially lower level of expression in advanced stage of colon cancer cases was observed." (PMID 30400781, 2018). "GPNMB overexpression in HCT116 colon cancer cell line decreased cell proliferation [(24 h, P = 0.02), (48 h, P < 0.001, 72 h, P = 0.007)], invasion (p < 0.05) and migration (p > 0.05) compared to the mock-transfected cells." (PMID 30400781, 2018). "Here, we present a detailed analysis of GPNMB methylation status, expression and function in pre-neoplastic and neoplastic clinical specimens and in colon cancer cell lines to shed light on the potential role of this gene’s methylation in colorectal tumorigenesis." (PMID 30400781, 2018). "The level of GPNMB methylation was variable at different stages of colon cancer." (PMID 30400781, 2018). "Thus, lower expression levels of GPNMB might account for higher aggressiveness and fast progression of colon tumors." (PMID 30400781, 2018). "Therefore, the higher methylation level of GPNMB in AA might partly account for the high aggressiveness and fast progression of colon tumors in AA." (PMID 19750230, 2009). "GPNMB CpG sites at the promoter region were highly methylated in the three colon cancer cell lines while it was not methylated in the blood DNA." (PMID 30400781, 2018). "The expression levels of GPNMB in human colon cancer cell lines (SW480, RKO, HCT116, and Colo320) were shown to decrease with higher levels of methylation pointing to a potentially dominant methylation effect on GPNMB expression." (PMID 30400781, 2018).
liver cirrhosis (3 papers, 2015 to 2025). "Serum GPNMB levels significantly increased in the patients with stage 4 manifesting liver cirrhosis compared with stages 1–3 without liver cirrhosis (26.92 ± 10.76 v.s." (PMID 26581806, 2015).
metabolic dysfunction-associated steatotic liver disease (3 papers, 2024 to 2026). Metabolic dysfunction-associated steatotic liver disease (MASLD, formerly known as nonalcoholic fatty liver disease or NAFLD) is a type of liver disease that is not caused by alcohol. "This included specific reductions in inflammatory genes, GPNMB, CCL3, MMP12, and EPHB2, which were up-regulated in humans and animal models of metabolic dysfunction-associated steatotic liver disease (MASLD) or metabolic dysfunction-associated steatohepatitis (MASH)." (PMID 39282008, 2024).
osteoarthritis (3 papers, 2010 to 2023). A noninflammatory degenerative joint disease occurring chiefly in older persons, characterized by degeneration of the articular cartilage, hypertrophy of bone at the margins and changes in the synovial membrane. "In addition to its diverse roles in normal cells, aberrant GPNMB/OA expression has been linked to various pathological disorders such as glaucoma, kidney disease, osteoarthritis and several types of cancer, including: uveal melanoma, glioma, hepatocellular carcinoma and cutaneous melanoma." (PMID 20711474, 2010). "Alternatively, six of the top concordant genes (HTR7, TRAK1, LAMA4, HS6ST1, PDE4A, GPNMB) at 52 weeks have been documented in prior osteoarthritis literature." (PMID 37134114, 2023). "In addition, GPNMB/OA expression is up-regulated in bone pathologies such as osteoarthritis and during fracture repair." (PMID 20711474, 2010).
osteoporosis (3 papers, 2011 to 2025). A condition of reduced bone mass, with decreased cortical thickness and a decrease in the number and size of the trabeculae of cancellous bone (but normal chemical composition), resulting in increased fracture incidence. "The results were that GPNMB-EVs significantly promoted the bone marrow mesenchyme and the proliferation of stem cells, and GPNMB-EVs activated Wnt/β-catenin signals to stimulate the osteogenesis of BMSCs, which indicated that GPNMB-EVs have broad potential as a cell-free therapy for osteoporosis." (PMID 35323799, 2022).
renal carcinoma (3 papers, 2010 to 2021). A carcinoma arising from the epithelium of the renal parenchyma or the renal pelvis. "TFE3 knockdown reduced GPNMB expression in renal cancer cells harboring either TFE3 translocations or FLCN inactivation." (PMID 21209915, 2010). "GPNMB expression was investigated in renal cancer cells, mouse embryo fibroblast cells, and mouse and human renal carcinomas under conditions of FLCN inactivation." (PMID 21209915, 2010). "We found that GPNMB expression, which is regulated by MiTF, was greatly elevated in renal cancer cells harboring either TFE3 translocations or FLCN inactivation." (PMID 21209915, 2010). "GPNMB is a transmembrane protein frequently upregulated in a wide variety of tumors, including lung and renal cancer, yet it is unclear whether GPNMB overexpression in itself is tumorigenic." (PMID 33459596, 2021). "Moreover, FLCN knockdown induced GPNMB expression in FLCN-restored renal cancer cells." (PMID 21209915, 2010).
renal cell carcinoma (3 papers, 2022 to 2025). "Studies have confirmed that serum GPNMB levels significantly increase in renal cell carcinoma patients with acquired resistance to immune checkpoint inhibitors." (PMID 41180454, 2025). "In renal cell carcinoma, GPNMB expression is closely related to bone metastasis, which is a poor prognostic factor; in terms of poor prognostic factors, they are the same as ours." (PMID 36061142, 2022).
type 2 diabetes (3 papers, 2020 to 2026). "Urinary concentrations of GPNMB failed to confer prognostic value for renal function decline beyond established risk factors in patients with type 2 diabetes, despite correlating with the severity of albuminuria." (PMID 32425885, 2020).
viral infection (3 papers, 2023 to 2025). "Similar to the findings in viral infection, we also noted that GPNMB disrupted the fusion of autophagosomes with lysosomes upon bacterial infection." (PMID 40038549, 2025). "In this study, we investigated the antiviral role of host GPNMB in viral infection." (PMID 37112900, 2023). "The data also indicate that GPNMB is context dependent with the present function set in the matrix of timing for GPNMB+ moDC and IL-33+ basal ESC interaction at 1–2 weeks after viral infection." (PMID 39052353, 2024). "Taken together, the knockdown of endogenous GPNMB expression in target cells results in the increased replication of PRRSV, indicating that GPNMB plays an important role in the viral infection process." (PMID 37112900, 2023). "Taken together, our data demonstrate that GPNMB inhibits PRRSV replication by inhibiting the autophagosome-lysosome fusion and provides a novel therapeutic target for virus infection." (PMID 37112900, 2023). "However, there have been no reports concerning the relationship between GPNMB and virus infection." (PMID 37112900, 2023).
adenoma (2 papers, 2018 to 2022). A neoplasm arising from the epithelium. "Our data indicate a high methylation profile leading to a lower GPNMB expression in adenoma and CRC samples." (PMID 30400781, 2018). "Our results from the IHC analysis of TMA indicated a reduction of GPNMB protein levels in adenoma and tumor tissues (both epithelial and stroma)." (PMID 30400781, 2018). "Advanced adenomas (> 1 cm with villous component and/or high grade dysplasia) samples had a significantly higher GPNMB methylation frequency than normal colon samples (42/48 [88%] vs. 1/20 [5%]; P < 0.001)." (PMID 30400781, 2018). "The investigation of GPNMB promoter methylation in adenoma and advanced adenoma revealed 76% (16/21) and 94% methylation frequency (45/48), respectively." (PMID 30400781, 2018). "Also, GPNMB was more frequently methylated in advanced adenoma than in matched normal mucosa from three patients (3/3 [100%] vs. 1/3 [33.3%]; P < 0.001)." (PMID 30400781, 2018). "It is tempting to speculate that the increase in GPNMB methylation in adenoma and tumor cases is directly responsible for the reduced GPNMB expression." (PMID 30400781, 2018). "This outcome suggests that GPNMB methylation takes place early in the adenoma-carcinoma sequence." (PMID 30400781, 2018). "Indeed, our analysis of 3 advanced adenomas and their matched normal DNA revealed higher methylation levels in the lesions pointing to a role of GPNMB methylation in the neoplastic process." (PMID 30400781, 2018). "As such, GPNMB might be useful as a biomarker of adenomas with high carcinogenic potential." (PMID 30400781, 2018). "Therefore, we aimed to examine the role and methylation status of Glyco Protein Non-Metastatic GPNM B (GPNMB) gene in normal, adenoma and CRC in African American (AA) patients." (PMID 30400781, 2018). "Finally, the frequency of GPNMB methylation in non-advanced adenoma differed statistically from that in the normal mucosa (16/21 [76%] vs. 1/20 [5%]; P < 0.001)." (PMID 30400781, 2018).
alpha-synucleinopathy (2 papers, 2018 to 2025). "No such GPNMB signal was evident in the pure alpha-synucleinopathy of aSYN-overexpressing transgenic mice." (PMID 30315256, 2018).
alveolar soft part sarcoma (2 papers, 2015 to 2023). An alveolar soft part sarcoma occurring in adults. "In support of GPNMB as a therapeutic target in cancer, a previous study of ASPSCR1-TFE3 fusion-driven alveolar soft part sarcoma also demonstrated increased GPNMB expression, and Gpnmb silencing in a mouse model of this disease inhibited cell migration, suggesting a role in metastasis." (PMID 37095531, 2023). "GPNMB is expressed highly in several OS xenografts [and also in one alveolar soft part sarcoma (ASPS) examined]." (PMID 26380223, 2015).
Amyloidosis cutis dyschromica (2 papers, 2021 to 2025). "Human mutations of GPNMB cause recessive and semi-dominant amyloidosis cutis dyschromica, a condition characterized by amyloid deposition in the papillary dermis; remarkably, though, the GPNMB protein is not a constituent of amyloid deposits." (PMID 34207849, 2021). "Amyloidosis Cutis Dyschromica (ACD, OMIM #617920) is a rare autosomal recessive or dominant disorder caused by Glycoprotein Non-Metastatic b (GPNMB) gene mutation, and characterized by clinically diffuse speckled hyper-/hypopigmentation and pathologically dermal amyloid deposition." (PMID 39487057, 2025).
astrocytoma (2 papers, 2010 to 2015). "The overall expression of GPNMB was higher in GBM than in meningioma and grade III astrocytoma samples." (PMID 25658639, 2015).
brain tumor (2 papers, 2012 to 2024). "GPNMB is a complex glycoprotein with multiple glycoforms in brain tumor cells as seen in previous Western blotting including those from murine brain tumor exosomes." (PMID 22848702, 2012).
cardiac sarcoidosis (2 papers, 2023 to 2025). Sarcoidosis affecting the tissues of the heart. "Moreover, GPNMB (transmembrane glycoprotein NMB) emerged as a potential biomarker for multinucleated giant cells associated with cardiac sarcoidosis." (PMID 38250062, 2023). "Also, upregulation of GPNMB in giant cells in conjunction with macrophages expressing MHC Class II has been described as a distinct morphological feature that differentiates cardiac sarcoidosis from giant cell myocarditis." (PMID 40928208, 2025). "In cardiac sarcoidosis, GPNMB+ (transmembrane glycoprotein NMB) multinucleated giant cells encased by macrophages expressing MHC Class II showed subsequent mammalian target of rapamycin activation and have been identified as a distinct morphological feature." (PMID 40928208, 2025).
cataract (2 papers, 2023 to 2024). Partial or complete opacity of the crystalline lens of one or both eyes that decreases visual acuity and eventually results in blindness. "Increased circulating GPNMB levels are associated with DM and cataract and can be used as a biomarker of DM-associated cataract." (PMID 36875463, 2023). "In addition, increased GPNMB in blood circulation was reported to be a potential biomarker in T2- associated cataracts." (PMID 38790981, 2024). "The ability of serum GPNMB levels to predict the presence of cataract was 0.783, based on ROC curve analysis (asymptotic significance: <0.001)." (PMID 36875463, 2023). "The results showed higher GPNMB levels in subjects with DM or cataract than in control subjects." (PMID 36875463, 2023). "In this study, elevated serum levels of GPNMB were determined in subjects with DM and cataract." (PMID 36875463, 2023). "In addition, serum GPNMB levels were independently correlated with both DM and cataract." (PMID 36875463, 2023). "Serum GPNMB levels were higher in diabetic individuals and subjects with cataract than in those without DM or cataract." (PMID 36875463, 2023). "Circulating serum GPNMB levels were higher in subjects with cataract than those without cataract." (PMID 36875463, 2023).
chronic kidney disease (2 papers, 2014 to 2025). Impairment of the renal function secondary to chronic kidney damage persisting for three or more months. "LEP is an energy metabolism hormone that enhances mineralization both in bone and in vascular tissue while GPNMB, is a glycoprotein implicated in end-stage renal disease (ESRD) a pathological condition associated to ectopic calcifications." (PMID 25380738, 2014).
chronic obstructive pulmonary disease (2 papers, 2020 to 2025). A chronic and progressive lung disorder characterized by the loss of elasticity of the bronchial tree and the air sacs, destruction of the air sacs wall, thickening of the bronchial wall, and mucous accumulation in the bronchial tree. "gpNMB is significantly increased in several unrelated diseases – notably patients with inflammatory respiratory diseases such as chronic obstructive pulmonary disease patients." (PMID 41152894, 2025).
Cirrhosis (2 papers, 2021 to 2024). A chronic disorder of the liver in which liver tissue becomes scarred and is partially replaced by regenerative nodules and fibrotic tissue resulting in loss of liver function. "Finally, our scRNAseq analysis shows the presence of DAMs in the liver of NAFLD patients, which share the same phenotype, including expression of TREM2, CD9, GPNMB, MHCII (HLA-DRB1), C1QA, and CLEC10A, as those found in the livers of patients with NASH and cirrhosis." (PMID 38280848, 2024).
cognitive decline (2 papers, 2023 to 2025). "Moreover, our findings demonstrated that CSF GPNMB concentrations had already increased in the early clinical stages of cognitive decline (MCI) and continued to rise with disease severity." (PMID 37510803, 2023). "In our study, we assessed the GPNMB levels in the CSF of AD patients and a control group (i.e., individuals without cognitive decline)." (PMID 37510803, 2023). "Thus, this relationship between GPNMB, YKL-40, and Tau proteins can be interpreted as the influence of neuroinflammation on accelerated neurodegeneration, which is reflected by the progressive cognitive decline in patients." (PMID 37510803, 2023).
Cognitive impairment (2 papers, 2023 to 2025). Abnormal cognition is characterized by deficits in thinking, reasoning, or remembering. "By contrast, silencing of GPNMB exacerbated CO poisoning-induced cognitive impairment in model rats." (PMID 40653468, 2025). "Furthermore, GPNMB attenuated cognitive impairment, oxidative stress and neuronal ferroptosis of rats with DEACMP." (PMID 40653468, 2025).
cutaneous melanoma (2 papers, 2020 to 2022). A primary melanoma arising from atypical melanocytes in the skin. "In breast and cutaneous melanoma, the expression of GPNMB is far lower, and GPNMB expression has been observed to be stable over time." (PMID 32823698, 2020). "Additionally, melanocytic markers such as glycoprotein NMB (GPNMB) and MLANA have increased expression, accounting for the cutaneous melanoma phenotype seen with this hereditary syndrome." (PMID 36421797, 2022).
diabetic retinopathy (2 papers, 2023 to 2024). "Another study that concentrated on diabetic retinopathy—a microvascular complication characterized by aberrant angiogenesis—found that GPNMB knockdown attenuated retinal angiogenesis stimulated by high glucose both in vivo and in vitro." (PMID 36875463, 2023).
ependymoma (2 papers, 2024). A WHO grade II, slow growing tumor of children and young adults, usually located intraventricularly. "We stained adjacent tissue sections for CA9, which is expressed by mesenchymal-like ependymoma tumor cells, IBA1, which is expressed by microglia, and GPNMB, which is expressed by DAM." (PMID 39561717, 2024). "We stained adjacent tissue sections for CA9, which is expressed by mesenchymal-like ependymoma tumor cells, IBA1, which is expressed by microglia, and GPNMB, which is expressed by DAM23." (PMID 36798206, 2024).
epilepsy (2 papers, 2017 to 2025). A brain disorder characterized by episodes of abnormally increased neuronal discharge resulting in transient episodes of sensory or motor neurological dysfunction, or psychic dysfunction. "GPNMB knockdown is capable to facilitate neuronal loss, apoptosis, and neuroinflammation of the hippocampus in pilocarpine-induced epilepsy." (PMID 40367036, 2025).
fatty liver disease (2 papers, 2015 to 2018). A reversible condition wherein large vacuoles of triglyceride fat accumulate in liver cells via the process of steatosis. "In this study, we also emphasize the importance of circulating GPNMB in fatty liver disease as a biomarker and therapeutic target." (PMID 26581806, 2015). "Therefore, GPNMB could potentially link AMPK activation and fatty liver disease." (PMID 29799853, 2018).
gastric tumor (2 papers, 2010 to 2023). "For the target gene GPNMB, elevation of expression was observed in primary gastric tumors (p-value = 1.11e-8; E-GEOD-15460)." (PMID 20507635, 2010). "The highest gene expression levels in the gastric tumor dataset were observed for AJUBA (1.44 × 1014), GPNMB (1.11 × 1014) and CD80 (1.09 × 1014)." (PMID 37765273, 2023).